PLAUR (plasminogen activator, urokinase receptor)
Diseases named in the same sentence as PLAUR in open-access papers (continued):
Sharing a sentence is not in itself a finding about the gene and the disease.
COVID-19 (19 papers, 2021 to 2025). A disease caused by infection with severe acute respiratory syndrome coronavirus 2. "We identified PLAUR rs2302524 as a single nucleotide polymorphism (SNP) associated with lung involvement in COVID-19 patients." (PMID 36555850, 2022). "In our screening study, PLAUR rs2302524 was found to be independently associated with the severity of lung involvement in COVID-19 patients." (PMID 36555850, 2022). "We identified PLAUR rs2302524 as the SNP associated with lung involvement in COVID-19 patients." (PMID 36555850, 2022). "PLAU and PLAUR expression was also observed in a fraction of cells from a pro-fibrogenic KRT17+ KRT5- population in COVID-19 and PF patients, though the overall number of PLAU+ and PLAUR+ cells in this population was still low (median normalized expression 0)." (PMID 36674896, 2023). "Our findings demonstrate that the lung monocytes/macrophages serve as a main source of PLAUR expression, which was significantly decreased in COVID-19 and PF." (PMID 36674896, 2023). "Among all epithelial cells, only airway basal cells were detected to persistently express PLAU and PLAUR, and their expression was significantly decreased in COVID-19 and PF patients." (PMID 36674896, 2023). "Another analysis of bulk BALF transcriptomes also demonstrated PLAUR downregulation in COVID-19 patients." (PMID 36674896, 2023). "Therefore, PLAUR expression was significantly decreased in epithelial and monocyte/macrophage cells from COVID-19 patients as compared to control samples." (PMID 36674896, 2023). "Single-cell RNA sequencing (scRNAseq) studies in severe COVID-19 revealed an abnormally expanded circulating myeloid cell compartment as well as an enriched expression of urokinase-type plasminogen activator receptor (PLAUR gene, expressing uPAR protein)." (PMID 34777349, 2021). "We found that the CD11chighHLA-DRlow myeloid cell subsets were highly abundant in patients with severe COVID-19 both in the circulation and in the airways on these analyses as well as noted a highly enriched expression of PLAUR in these CD11chighHLA-DRlow myeloid cells." (PMID 34777349, 2021). "In COVID-19 and PF patients, the expression of PLAU and PLAUR in these cells was significantly decreased as compared to the control (p < 0.0001 vs. control)." (PMID 36674896, 2023). "The significant decrease in PLAUR mRNA expression in basal epithelial cells and lung monocytes/macrophages and its relative decrease at the background of the significantly increased amount of its ligand might also contribute to the pathogenesis of pulmonary fibrosis in COVID-19." (PMID 36674896, 2023). "Lung cells from COVID-19 patients show expression of HIF1α, TLR2, TLR4, PFKFB3, CXCR1, −2 and −4, SOD2, PLAUR and other genes expressed in immature myeloid cells." (PMID 33345622, 2021). "Finally, to identify independent prognostic factors of COVID-19-related lung damage severity, a multivariable logistic regression was performed, with age, sex, CRP, fibrinogen, D-dimer, thrombin time, uPAR serum level and PLAUR rs2302524 as independent variables." (PMID 36555850, 2022). "In contrast to patients with COVID-19, healthy individuals display only a single positive feedback loop between fibronectin (FN1) and plasminogen activator, urokinase receptor (PLAUR) not involving any cytokines or chemokines, as expected from the transcriptional analysis." (PMID 33536217, 2021).
metastatic disease (18 papers, 2003 to 2023). "Recognizing the PLAUR gene as an important mediator of proteolytic networks in the tumor microenvironment, we further investigated uPAR protein levels and association with metastatic disease." (PMID 35480116, 2022). "The highest differentially expressed genes in metastatic (MET and PRI+) versus non-metastatic tumors (PRI-) and SES included PLAU, PLAUR, MMP1, MMP10, MMP13, ITGA5, VEGFA, and various inflammatory cytokine genes." (PMID 35480116, 2022).
Sepsis (18 papers, 2007 to 2026). Sepsis is defined as life-threatening organ dysfunction caused by a dysregulated host response to infection. "Of note, soluble PLAUR is also a biomarker of disease severity in other conditions associated with immunothrombosis and alveolar damage such as sepsis." (PMID 38803346, 2024).
bladder cancer (17 papers, 2015 to 2025). "The gene expression of PLAUR and IL-1β is shown in bladder carcinoma." (PMID 36430487, 2022).
non-small cell lung carcinoma (16 papers, 2007 to 2025). A group of at least three distinct histological types of lung cancer, including non-small cell squamous cell carcinoma, adenocarcinoma, and large cell carcinoma. "Our analysis was consistent with similar analysis completed in human non-small cell lung cancer in which PLAU, PLAUR, IL1R2, CD274, OSM, and CXCL8 were reported to be significantly enriched in TANs relative to circulating neutrophils." (PMID 39932553, 2025).
pulmonary fibrosis (16 papers, 2016 to 2026). Chronic progressive interstitial lung disorder characterized by the replacement of the lung tissue by connective tissue, leading to progressive dyspnea, respiratory failure, or right heart failure. "Of note, type 3 fibroblasts exhibited an elevated expression of both PLAU and PLAUR in pulmonary fibrosis, while in mesothelial cells, only PLAUR expression was elevated (p < 0.0001 vs. control)." (PMID 36674896, 2023). "Pulmonary fibrosis was associated with the elevated expression of PLAU and PLAUR in mesenchymal cells: PLAU in type 3 fibroblasts, PLAUR in type 3 fibroblasts and mesothelial cells." (PMID 36674896, 2023).
asthma (15 papers, 2009 to 2023). "uPAR gene (PLAUR) polymorphisms are associated with asthma development risk and lung function decline, implicating a role in patient airway remodeling." (PMID 37876037, 2023). "PLAUR rs2302524 was previously linked to asthma susceptibility and to a decline in lung function in asthma, basal epithelial proliferation in asthmatic individuals and baseline lung functioning in smokers." (PMID 36555850, 2022). "And PLAUR is associated as an inflammation-related gene with diseases or processes, such as asthma, myocardial infarction, and reduced lung function." (PMID 35720085, 2022). "PLAUR has been identified as an asthma-associated gene showing association between single nucleotide polymorphisms and asthma susceptibility, bronchial hyper-responsiveness (BHR) and decline in lung function." (PMID 34065716, 2021). "Other genes associated with 3 or fewer gene sets have also been associated with asthma such as Plasminogen Activator, Urokinase Receptor (PLAUR) and Serpin Family E Member 2 (SERPINE2), and several additional genes were first identified here." (PMID 28886691, 2017). "Recently we have performed linkage and association analyses utilising three populations including 587 UK and Dutch asthma families and identified the urokinase plasminogen activator receptor gene (uPAR or PLAUR) as an asthma susceptibility gene." (PMID 19638192, 2009). "We have previously identified PLAUR as an asthma susceptibility gene." (PMID 24249636, 2014). "A recent review has compiled data describing that individuals with asthma may be predisposed to features of airway remodeling based on single nucleotide polymorphisms in remodeling-associated genes, including IL13, PLAUR, VEGFA, and CHI3L1." (PMID 37773065, 2023). "Similarly, in further independent studies, we have shown that PLAUR SNPs are associated with baseline lung function in smokers and that uPAR is elevated in the airway epithelium in asthma." (PMID 24249636, 2014). "PLAUR may play a role in the pathogenesis of airway remodeling in asthma." (PMID 21603163, 2011). "Urokinase receptor (PLAUR, uPAR), also upregulated by S1P in ASM cells, was reported to be increased in patients with asthma and led to attenuated wound repair, a process contributing to development and progression of airway remodelling in asthma." (PMID 25041788, 2014). "However, based on our data, we can speculate that it is repetitive exposure, rather than enhanced responsiveness, to S1P that determines increased expression of pro-remodelling factors observed in asthma, that is HBEGF, RGS4 and PLAUR." (PMID 25041788, 2014).
atherosclerosis (15 papers, 2014 to 2025). A disease characterized by the build-up of fatty material and calcium deposition in the arterial wall resulting in partial or complete occlusion of the arterial lumen. "Recent studies have identified PLAUR (Plasminogen activator, urokinase receptor) as an effective diagnostic marker for atherosclerosis lesion progression." (PMID 40607379, 2025). "Elevated expression levels of PLAUR have been correlated with the severity of atherosclerosis in both human and mouse models." (PMID 40607379, 2025). "PLAUR is a gene coding for urokinase plasminogen activator surface receptor (uPAR) that is elevated in atherosclerosis and in many cancer types." (PMID 39062148, 2024). "The findings of further experiments and bioinformatic analyses revealed that CSF1R and PLAUR are important genes for the development of atherosclerosis." (PMID 37810795, 2023). "CSF1R and PLAUR are key hub genes of foam cells and may play an important role in the biological process of atherosclerosis." (PMID 37810795, 2023).
hepatocellular carcinoma (15 papers, 2013 to 2025). A malignant tumor that arises from hepatocytes. "The upregulation of PLAUR, S100A4, S100A6, and FGFR1 in mature B cells was involved in disease‐associated cellular migration and tissue invasion, which may influence hepatocellular carcinoma with persistent liver injury." (PMID 41190282, 2025).
breast tumor (13 papers, 2001 to 2026). "Using PrognoScan analyses, we observed that high level of PLAUR mRNA expression in breast tumors was associated with poor distant metastasis-free survival (DMFS) and overall survival (OS)." (PMID 37345070, 2023). "A similar trend in the elevated expression of the PLAUR gene was observed upon the analysis of different cancer types in the Oncomine database where the highest expression is seen in breast tumors relative to normal tissues." (PMID 32337090, 2020). "It should be noted that these sample sets only look at PLAUR gene expression and not uPAR protein and that they have been obtained from bulk tumor extraction mostly of primary and not metastatic breast tumors." (PMID 32337090, 2020).
diabetes (13 papers, 2013 to 2024). "PLAUR has been associated with the regulation of uPAR in a mechanism including vascular endothelial growth factor, interfering with the blood–retinal barrier that characterizes the early stages of vascular dysfunction in diabetes." (PMID 39062148, 2024).
leukemia (12 papers, 2015 to 2025). A malignant (clonal) hematologic disorder, involving hematopoietic stem cells and characterized by the presence of primitive or atypical myeloid or lymphoid cells in the bone marrow and the blood. "PLAUR, also known as CD87, has shown poor survival benefits in leukemias, with the potential to be used as a target for fusion protein therapy of PLAUR-expressing AML." (PMID 35536524, 2022).
lung adenocarcinoma (11 papers, 2019 to 2025). A carcinoma that arises from the lung and is characterized by the presence of malignant glandular epithelial cells. "Further, as PLAUR overexpression was shown to induce gefitinib resistance through the EGFR/p-AKT/surviving signaling pathway in cell models of human lung adenocarcinoma, strategies that downregulate PLAUR could also be explored to avoid EGFR-targeted resistance mechanisms." (PMID 35480116, 2022). "In addition, there is evidence that the expression of PLAUR is upregulated in fentinib-resistant lung adenocarcinoma cells, and PLAUR can induce gefitinib resistance in gefitinib-resistant human lung adenocarcinoma cells through the EGFR/p-AKT/survivin signaling pathway." (PMID 35675366, 2022). "At the same time, the expressions of HNRNPAB/PLAUR and SEMA3A were detected in the cancer and paracancerous tissues of a lung adenocarcinoma patient, as determined by IHC." (PMID 36091160, 2022). "We stained the lung adenocarcinoma TMA with antibodies against an EMT marker (E-cadherin 1 (CDH1), molecules included in the signature (SMAD7, PLAUR), and immune checkpoint markers." (PMID 30783512, 2019). "Furthermore, HNRNPAB/PLAUR and SEMA3A were considered by us as significant predictive target genes of the PTEN-related LINC00460/miR-150-3p axis in lung adenocarcinoma." (PMID 36091160, 2022).
medulloblastoma (11 papers, 2012 to 2026). A malignant, invasive embryonal neoplasm arising from the cerebellum. "Moreover, overexpression of PLAUR was shown to increase the activity of the WNT signaling to promote cancer stemness in medulloblastoma cells." (PMID 34950596, 2021).
oral squamous cell carcinoma (11 papers, 2014 to 2023). "The urokinase plasminogen activator receptor (uPAR), encoded by Plasminogen Activator, Urokinase Receptor (PLAUR), has been involved in angiogenesis, growth, and metastasis of many hematologic and solid tumors, and has recently been shown as a prognostic factor for oral squamous cell carcinoma." (PMID 32664456, 2020).
cervical cancer (10 papers, 2014 to 2025). A primary or metastatic malignant neoplasm involving the cervix. "Based on luciferase assays, researchers found that the hypoxia-induced overexpression of HIF-1α activated the transcriptional activity of the PLAUR promoter, thereby enhancing its expression in cervical cancer, so that the cervical cancer cells were more invasive under hypoxic conditions." (PMID 35864968, 2022).
rheumatoid arthritis (10 papers, 2018 to 2025). A chronic, systemic autoimmune disorder characterized by inflammation in the synovial membranes and articular surfaces. "PLAUR is the receptor of plasminogen activator (PLAU), which participates in various physiological functions such as wound healing and is also associated with rheumatoid arthritis, Quebec platelet disorder, and tumor angiogenesis and metastasis." (PMID 40224547, 2025). "In addition, recently, research found that PLAUR secretes several cytokines and chemokines and initiates inflammatory responses in macrophages and fibroblast-like synoviocytes through activation of the PI3K/Akt signaling pathways in rheumatoid arthritis." (PMID 35211477, 2021).
sarcoma (10 papers, 2011 to 2024). A usually aggressive malignant neoplasm of the soft tissue or bone. "Consistent expression of EGFR and uPAR (PLAUR mRNA) was found across human sarcomas in the Cancer Genome Atlas (TCGA); similarly, both proteins were found to be expressed in a synovial sarcoma tissue microarray." (PMID 32630411, 2020). "EGFR and PLAUR gene expression were detectable in 100% of samples regardless of sarcoma type with a variation in intensity." (PMID 29218302, 2017).
neuroblastoma (8 papers, 2014 to 2025). Neuroblastoma (NB) is the most common solid, extracranial childhood tumor. "We found that the relapse of neuroblastoma after treatment is associated with the decrease in PLAUR expression." (PMID 35205745, 2022). "We found that high PLAUR expression before treatment initiation was significantly associated with poor overall survival and shorter relapse-free survival period in human neuroblastoma patients." (PMID 35205745, 2022). "These obtained data indicate that high PLAUR expression in neuroblastoma at the early stage is associated with worsened survival." (PMID 35205745, 2022). "Yet, the relapsed neuroblastomas exhibit a marked decrease in PLAUR expression, thus indicating that uPAR takes part in neuroblastoma progression." (PMID 35205745, 2022). "We demonstrate that the initially high PLAUR expression predicts poor survival in human neuroblastoma." (PMID 35205745, 2022). "However, relapsed neuroblastomas have a significantly decreased PLAUR expression." (PMID 35205745, 2022).
myocardial infarction (7 papers, 2009 to 2026). Gross necrosis of the myocardium, as a result of interruption of the blood supply to the area, as in coronary thrombosis. "PLAUR levels have been associated with vascular remodelling and monocyte adhesion in acute myocardial infarction." (PMID 19878584, 2009). "PLAU and PLAUR encode uPA and its receptor (uPAR), and functional variants in these genes may influence susceptibility to myocardial infarction." (PMID 41538664, 2026). "Meeting all the cutoff criteria across all the data set analyzed, MAN2A2/TNFRSF12A/SPP1/CSNK1D/PLAUR/PFKFB3/CXCL16 (herein we termed it MTSCPPC signature) was identified as a novel pathological signature of myocardial infarction and was used for subsequent analyses." (PMID 35163208, 2022).
Obesity (7 papers, 2015 to 2025). Accumulation of substantial excess body fat. "Individuals with obesity exhibited notably higher PLAUR expression in white adipose tissue, upregulated both mRNA expression and plasma levels of soluble PLAUR, positively correlating with metabolic parameters, including BMI." (PMID 38562155, 2024). "Among the three genetic predispositions associated with airway remodeling, PLAUR, and CHI3L1 are potentially linked to obesity." (PMID 38562155, 2024). "Although the correlations between most of the DEGs we identified in this study and obesity are well-established, such as SERPINE1, PLAUR, CA3, and TIMP1." (PMID 35894174, 2022). "Interestingly, our data suggest that inflammation modulated by IL-1β, IL-6, PLAUR, and CCL2 in the VAT could be related to anxiety and mood disorders as long as patients are not in an obesity state." (PMID 30504920, 2018).
Arthritis (5 papers, 2009 to 2024). Inflammation of a joint. "Moreover, PC downregulated the expression of PLA2G4A (−1.61-fold change), PLAUR (−1.94-fold change), and MMP9 (−1.91-fold change), all of which have been previously implicated in the pathogenesis of arthritis." (PMID 23936839, 2013).
autoimmune disease (5 papers, 2016 to 2025). A disorder resulting from loss of function or tissue destruction of an organ or multiple organs, arising from humoral or cellular immune responses of the individual to their own tissue constituents. "PLAUR, a receptor for urokinase-type plasminogen activator (uPA), has been investigated in the context of autoimmune disorders and tissue remodeling." (PMID 39224582, 2024).
brain tumors (5 papers, 2016 to 2024). "PLAU and its receptor (PLAUR/uPAR) are mainly involved in invasion and cell proliferation, and their increased expression is correlated with a wide range of human diseases, including autism, Alzheimer’s, AIDS dementia, cerebral malaria and brain tumors." (PMID 27846841, 2016).
chronic obstructive pulmonary disease (4 papers, 2009 to 2025). A chronic and progressive lung disorder characterized by the loss of elasticity of the bronchial tree and the air sacs, destruction of the air sacs wall, thickening of the bronchial wall, and mucous accumulation in the bronchial tree. "In the current study we tested the hypothesis that PLAUR single nucleotide polymorphisms (SNPs) determine baseline lung function and contribute to the development of Chronic Obstructive Pulmonary Disease (COPD) in smokers." (PMID 19878584, 2009).
esophageal cancer (4 papers, 2014 to 2022). A primary or metastatic malignant neoplasm involving the esophagus. "The statistically higher expressions of PLAUR, BIK, DRAM2, RNF41, STK38, ATG5, and PARP1 were measured in esophageal cancer than those in normal tissue, while statistically significant differences were also detected between ESCC and esophageal adenocarcinoma (EAC)." (PMID 32974198, 2020).
kidney damage (4 papers, 2019 to 2025). "PLAUR-deficient mice exhibit pathological abnormalities related to PLAUR proteolytic function, including dermal fibrosis and exacerbation of experimentally induced kidney fibrosis and nephropathy." (PMID 31105713, 2019).